CXCL8 (C-X-C motif chemokine ligand 8)
Diseases named in the same sentence as CXCL8 in open-access papers (continued):
Sharing a sentence is not in itself a finding about the gene and the disease.
cervical carcinoma (continued). "However, the high expression of CXCL8, TNFAIP6, CXCL5 and CDA in cervical cancer tissues was associated with a poor patient prognosis." (PMID 34174849, 2021). "In addition, miR-302c-3p and miR-520a-3p suppressed the proliferation of cervical carcinoma cells by targeting CXCL8." (PMID 34833360, 2021). "CXCL8, a proinflammatory oncogene is highly expressed in cervical cancer tissues." (PMID 31366565, 2019). "The prognostic value of CXCL8 protein was further identified in cervical cancer patients." (PMID 28883082, 2017). "However, due to the limited sample size of patients in our study, further studies would be needed to verify these findings and establish the role of CXCL8 as a reliable clinical predictor for the outcome of cervical cancer patients." (PMID 28883082, 2017). "Due to cervical cancer patients with CXCL8 overexpression, CXCL8 signaling pathway inhibitors may have favorable effectiveness for cervical cancer patients." (PMID 28883082, 2017). "Furthermore, we confirmed that CXCL8 mRNA was highly expressed in cervical cancer tissues and cell lines compared with adjacent normal cervical tissues and cervical cancer cell lines." (PMID 28883082, 2017). "Furthermore, we conducted qRT-PCR, Western blot, and immunohistochemistry to determine CXCL8 mRNA and protein levels in normal cervical tissues and cervical cancer tissues." (PMID 28883082, 2017). "Regardless of clinical stage, lymph node metastasis, distant metastasis, histological type and histological grade, we found that CXCL8 protein high expression also served as a poor prognostic parameter in cervical cancer patients through univariate Cox regression analyses." (PMID 28883082, 2017). "CXCL8 high expression was a poor independent prognostic parameter for cervical cancer patients." (PMID 28883082, 2017). "Similarly, CXCL8 protein expression was shown to be overexpressed in human cervical cancer cell lines compared with normal cervical epithelial cells lines." (PMID 28883082, 2017). "The prognostic significance of CXCL8 was unclear in cervical cancer patients." (PMID 28883082, 2017). "However, the clinical and prognostic significance of CXCL8 in cervical cancer is poorly understood." (PMID 28883082, 2017). "The status of CXCL8 expression in cervical cancer was still unknown." (PMID 28883082, 2017). "For example, CXCL8, CLEC9A, and TAB2 have been identified as crucial mRNA biomarkers related to immune microenvironment alterations in cervical cancer." (PMID 40003691, 2025). "We employed RT-PCR to ascertain the mRNA expression levels of CXCL8 and CXCL10 in human cell lines derived from cervical cancer." (PMID 38275602, 2024). "For example, CXCL8 increases in the presence of E6/E7 of HPV-16 and -18 in cervical cancer samples, and CXCL8 expression is predictive of a worse survival rate." (PMID 39727946, 2024). "Our study further validates previous findings that CXCL8 and CXCL10 expression is elevated in cervical cancer." (PMID 38532933, 2024). "This study revealed that the presence of HPV16 and 18 oncogenes significantly alter the expression of CCL28, CXCL1, CXCL2, CXCL3, CXCL6, CXCL8, CXCL10, and CXCL11; overexpression of those chemokines was also confirmed in cervical cancer biopsies." (PMID 37893029, 2023). "Epiregulin was positively correlated with most chemokines, such as CXCL1, CXCL2, CXCL3, CXCL5, CXCL6, CXCL8, and CCL20, in most types of cancer, including cervical cancer." (PMID 37020674, 2023). "CXCL8 can stimulate proliferation and survival via autocrine activation in CRC, cervical cancer, and LC, or via the ERK1/2 pathway in NSCLC." (PMID 31991604, 2020). "However, the clinical and prognostic significance of CXCL8 in cervical cancer is still unknown." (PMID 28883082, 2017).
cervical carcinoma (continued). "Furthermore, we analyzed a cohort that included 246 cervical cancer patients from The Cancer Genome Atlas database, and found that patients with high level of CXCL8 had shorter overall survival compared with patients with low level of CXCL8, which was consistent with our result." (PMID 28883082, 2017). "SF regulated the expression of chemokines CCL2, CCL5, CXCL1, CXCL2, CXCL3, CXCL8 (IL-8), and CXCL11 all of which play vital role in cervical cancer inflammation and tumorigenesis." (PMID 27446968, 2016). "To investigate the role of key genes in cervical cancer survival prognosis, we comprehensively analyzed the correlation between the expression levels of EFNA1, CXCL8, and PPP1R14A, and various clinical features, including age, stage, tumor grade (T), lymph node status (N), and metastasis status (M)." (PMID 40406253, 2025). "For instance, in cervical cancer, TNF activates the NF-κB signaling pathway, inducing the expression of chemokines such as CXCL1 and CXCL8, which promotes the infiltration of neutrophils and macrophages, thereby facilitating tumor progression and immune evasion." (PMID 40517358, 2025). "Furthermore, this phenomenon was validated by analyzing the expression of CXCL8 and CXCL10 in both normal and cervical cancer tissues." (PMID 38275602, 2024). "Our results revealed that expression of CXCL1, CXCL2, CXCL3, and CXCL8 increases in the presence of E6/E7 of HPV16 and 18, are overexpressed in CC biopsies, and that their higher expression is related to a worse prognostic survival in cervical cancer." (PMID 37893029, 2023). "AKIP1 in cervical cancer cells stimulates the expression of CXCL1, CXCL2, and CXCL8." (PMID 34833360, 2021). "Therefore, AKIP1 is critical to the angiogenesis and growth of cervical cancer by increasing levels of the NF-κB-dependent chemokines CXCL1, CXCL2, and CXCL8." (PMID 34833360, 2021). "In summary, it can be said that the high expression of CXCL8 is a negative independent prognostic parameter for cervical cancer patients." (PMID 34833360, 2021). "Since the HDAC inhibition by vorinostat has been very effective in the treatment of CTCL, in this study, we have investigated whether vorinostat induces the CXCL8 expression in CTCL Hut-78 cells, as well as in the widely used cervical cancer HeLa cells." (PMID 29050320, 2017).
Anxiety (72 papers, 2006 to 2026). Intense feelings of nervousness, tension, or panic often arise in response to interpersonal stresses. "After controlling clinical measures for age + gwk + BMI, chemokines such as IL-8/CXCL8, MCP-1/CCL2 and MIP-1β/CCL4 were found associated with high scores for anxiety (p < 0.05) in the ANX group." (PMID 34863117, 2021).
Stroke (72 papers, 2007 to 2025). Sudden impairment of blood flow to a part of the brain due to occlusion or rupture of an artery to the brain. "CXCL8 has previously been implicated in enhancing neutrophil infiltration across the BBB in adult stroke models." (PMID 36609414, 2023). "Our study found that plasma CXCL8 (interleukin-8) is linked with long-term outcomes post-stroke." (PMID 38861234, 2025). "Additionally, an elevation in CXCL8 blood levels is associated with a greater risk of poor functional outcomes after a year and a higher likelihood of death within 5 years of experiencing a stroke." (PMID 38861234, 2025). "A possible explanation is that plasma CXCL8 levels in this cohort are significantly higher in subjects with a history of stroke, and there are more of these individuals in the control than PD group." (PMID 33557896, 2021). "Have evidence that proinflammatory cytokines (e.g., TNF-α, IL-1, and IL-6), and chemokines (e.g., CC-chemokine ligand 2 (CCL2), CC-chemokine ligand 5 (CCL5), and chemokines chemokine (C-X-C motif) ligand 8 (CXCL8)) are transcriptional targets of NFAT5 in stroke." (PMID 38308370, 2024). "However, the prognostic value of other chemokines, such as CCL2, CCL5, or CXCL8, which have been studied in animal stroke models, remains unclear." (PMID 38861234, 2025). "Levels of IL-8 (CXCL8) and the acute-phase protein C-reactive protein (CRP) rise slightly later, with CRP peaking at approximately 48 h post-stroke." (PMID 40869247, 2025). "In a multivariate analysis adjusted for age, atrial fibrillation, pre-stroke dependency, NIHSS on admission and right-sided lesion, CXCL10 and CXCL8 still remained independent predictors of death." (PMID 38861234, 2025). "Plasma CXCL8 and CXCL10 show potential as prognostic biomarkers for stroke outcomes and as therapeutic targets suitable for reverse translation." (PMID 38861234, 2025). "In conclusion, plasma CXCL8 and CXCL10 show potential as both prognostic biomarkers for stroke outcomes and therapeutic targets." (PMID 38861234, 2025). "In the unstimulated saliva of stroke patients, we demonstrated significantly higher levels of chemotactic factors (CTACK/CCL27, IL-8/CXCL8, MIG/CXCL9, MIF) and growth factors (basic FGF, G-CSF, HGF, LIF, VEGF) compared to controls." (PMID 40221607, 2025). "In the pathological progression of stroke, gelatinases including MMP-2 and MMP-9, possess the ability to activate numerous pro-inflammatory agents, including chemokine CXCL-8, interleukin 1β, and tumor necrosis factor α." (PMID 30953513, 2019). "IL-17A, produced mainly by activated Th17 cells, can induce the secretion of a variety of stroke-related cytokines, such as IL-6, TNF-α, IL-1β, CXCL1 and CXCL8." (PMID 29262579, 2017). "Similarly, the pan-chemokine specific inhibitor NR58-3.14.3 also improved outcome in experimental stroke, while anti-CCL2 and CXCL8 antibodies decreased brain oedema and BBB permeability, respectively." (PMID 31281252, 2019).
leukemia (70 papers, 2000 to 2025). A malignant (clonal) hematologic disorder, involving hematopoietic stem cells and characterized by the presence of primitive or atypical myeloid or lymphoid cells in the bone marrow and the blood. "Druggability evaluation of the 12 identified risk proteins revealed that three (AXL, CXCL8, and PDIA3) are already recognized as drug development targets for leukemia, cancer, and inflammation." (PMID 41463415, 2025). "While CXCL1 has not previously been measured during febrile episodes in children with leukemia, CXCL8 has been extensively studied." (PMID 37919603, 2024). "It has been recently found that the gene that codes for interleukin-8 (CXCL8) is highly expressed in chemorefractory leukemia cells (T-ALL) and has been proposed to play several functions in T-ALL cells." (PMID 37885528, 2023). "Clusters 1–4 contained Dx cells that were enriched for CXCL8 and CXCR4, genes associated with the interaction between leukemia blasts and stromal cells." (PMID 35986270, 2022). "hIL-17 and hTNF-α synergistically or additively induced CXCL8 and CCL2 expression and consequently promoted primary human neutrophil and human leukemia monocytic cell migration, respectively." (PMID 35844613, 2022). "CXCR1-transfected and C5aR-transfected mouse leukaemia L1/2 BCs in response to CXCL8 and C5a, respectively; CCR4-transfected and CXCR2-transfected HEK-293 cells in response to CCL17 and CXCL8, respectively." (PMID 36341452, 2022). "Seeding and growth of different B-ALL cell lines in this leukemia BM niche model showed a progressive production of chemokines such as CCL2 and pro-inflammatory cytokines, including IL-6 and CXCL8." (PMID 33922612, 2021). "Ex vivo experiments from different research groups indicate that leukemia stimulation of primary BM-MSCs is able to specifically upregulate the expression of CCL2, CXCL10, CCL22, CXCL8, and CXCL1." (PMID 33922612, 2021).
ulcerative colitis (68 papers, 2009 to 2026). An inflammatory bowel disease involving the mucosal surface of the large intestine and rectum. "One study found that chemokine CXCL8 expression was upregulated in mucosal biopsies from patients with Crohn’s disease and ulcerative colitis and that this upregulation correlated with disease activity." (PMID 40540498, 2025). "We identified 141 action targets for Que, including CXCL8, and 5,752 potential targets related to UC using “ulcerative colitis” as a keyword." (PMID 39717557, 2024). "Increased CXCL8 expression was observed in ulcerative colitis but data for Crohn’s disease is controversial." (PMID 37063924, 2023). "C-X-C motif chemokine ligand 8 (CXCL8), also known as interleukin-8 (IL-8), is one of the most important proinflammatory factors and plays a vital role in many inflammatory diseases including ulcerative colitis." (PMID 36065195, 2022). "CXCL8 also plays a predominant role in the pathogenesis of many intestinal inflammatory diseases including Ulcerative colitis and IBD." (PMID 36093177, 2022). "For instance, the up-regulated expression of chemokines, such as CCL2, CCL3, CCL4, CCL7, CCL8 and CXCL8 has been shown in mucosal biopsies from patients with CD and ulcerative colitis, and this up-regulation correlated with the disease activity." (PMID 19421322, 2009). "Additionally, in a study on perfusates from patients with demonstrated elevated levels of CXCL1, the concentration of CXCL1 was 3 times higher than CXCL8/IL-8, which indicates that in ulcerative colitis, CXCL1 has a major function among CXCR2 ligands." (PMID 35806156, 2022). "In addition, in ulcerative colitis, a collaboration between the innate and adaptive immune system was recently proposed, as mucosal CD14+ monocyte-like cells induced CXCL8 in colonic memory CD4+ T-lymphocytes." (PMID 36725964, 2023). "Studies have reported significant differences in eRNA expression levels among multiple chemokine gene-related enhancer regions (including CXCL1-3, CXCL5-6 and CXCL8), which are all up-regulated in IBD, Crohn’s disease (CD), ulcerative colitis (UC) and controls using CAGE and qPCR." (PMID 35514959, 2022). "Additionally, mucosal biopsies from patients with ulcerative colitis show higher expression of another CXCR2 ligand: CXCL8/IL-8, which indicates that CXCL1 does not act alone but rather with other CXCR2 ligands." (PMID 35806156, 2022).
autoimmune disease (65 papers, 2010 to 2025). A disorder resulting from loss of function or tissue destruction of an organ or multiple organs, arising from humoral or cellular immune responses of the individual to their own tissue constituents. "CXCL1, CXCL2, and CXCL8/IL-8 are contributors to granulocyte and leukocyte migration, particularly in other autoimmune diseases such as multiple sclerosis and experimental autoimmune encephalomyelitis." (PMID 35885983, 2022). "In the present study, through the analysis of the PPI network of DE mRNAs, we identified several hub genes, including IL6, IL10, and CXCL8, which are important genes in autoimmune diseases and inflammatory pathways." (PMID 34284720, 2021). "The main function of Th17 cells is to produce various cytokines, such as IL-17, IL-21 and IL-22, which stimulate epithelial cells, fibroblasts and smooth muscle cells of the airway to secrete CXCL1 and CXCL8, thereby participating in autoimmune diseases." (PMID 34863307, 2021). "Similarly, MDX-018, targeting CXCL8, has shown efficacy in inhibiting tumor growth and treating autoimmune diseases." (PMID 41463415, 2025). "Elevated CXCL8 levels during chronic inflammation result in an enhanced recruitment of immune cells to the site of infection, which may lead to the development of autoimmune diseases following secretion of pro-inflammatory cytokines." (PMID 20507572, 2010). "This complex regulation of CXCL8 suggests that there is a need to further evaluate the signalling pathways in order to develop new treatment for diseases with elevated CXCL8 levels, such as AIDS and autoimmune diseases." (PMID 20507572, 2010).
breast tumor (65 papers, 2006 to 2026). "This was revealed not only by studies of tumor cell invasion and CXCL8 release, but also by in vivo analyses demonstrating the roles of PD-L1 N-linked glycosylation in determining the tumorigenic and metastatic activities of breast tumor cells." (PMID 37830552, 2023). "A recent study also showed that overexpression of TILRR in BT474, a human breast tumor cell line, significantly potentiates the expression of immune and inflammation-associated genes, including IL-6, IL-8/CXCL8, IP-10 (interferon gamma-induced protein 10)/CXCL10, MCP-1/CCL2, and RANTES/CCL5." (PMID 34360591, 2021). "The DC2_AREG was enriched in the tumor samples, especially in ovary, lung and breast tumors, while DC_CXCL8 was abundant in skin samples." (PMID 38972873, 2024). "Among the chemokine family, CXCL8 also showed significantly increased expression in de novo metastasized breast tumors." (PMID 37686617, 2023). "It was also found that breast tumor cells produced semaphorin D, which has increased CXCL8 production by osteoblasts and the levels of TRAP+ expressing cells in vitro." (PMID 32582148, 2020). "Similar roles for CXCL1/CXCL8 and their receptors in inducing EMT were implicated in several other publications of breast tumor cells." (PMID 32582148, 2020). "The dual roles of chemokines in the senescence context are nicely exemplified by a study on human pituitary tumor-transforming gene 1 (PTTG-1)-driven expression of CXCL1 and CXCL8 in breast tumor cells." (PMID 32582148, 2020). "Another study indicated that through the activities of the transcription factor Brachyury that has led to CXCL8 up-regulation in breast tumor cells, EMT processes were increased in adjacent cancer cells." (PMID 32582148, 2020). "In such studies, CXCL8 was noted in CM of breast tumor/senescent cells or was induced by chemotherapy and by different stimuli such as over-expression of the transcription factor Brachyury." (PMID 33585241, 2020). "Together, these findings suggest that tumors containing high levels of TNFα and TGFβ1 are enriched with the inflammatory and tumor-promoting mediators CCL2, CXCL8 and Cox-2, and that all three inflammatory mediators are coregulated in human breast tumors." (PMID 28553282, 2017). "Despite its ability to act alone in the tumor cells, RasG12V had a relatively minor effect on pro-malignancy activities in MCF-7 breast tumor cells (measured indirectly in terms of CXCL8 release), as compared to the inflammatory cytokines." (PMID 24598028, 2014). "Consequently, PD-L1 promotes breast tumor cell growth, CXCL8 release and invasion, as well as tumor growth and metastasis in vivo." (PMID 37830552, 2023). "During the in vitro conversion process of mesenchymal stromal cells in cancer-associated fibroblast by breast tumor cell (MDA-MB-231 and MCF-7)-conditioned media, TNF-alpha stimulation is responsible for the chemokines released (CCL2, CXCL8, and CCL5) by the tumor stromal cells." (PMID 37681908, 2023). "Different studies indicated that various types of chemotherapy share the ability to promote the release of ELR+ CXC chemokines—CXCL1, CXCL2, CXCL3, CXCL5, CXCL7 and CXCL8 (depending on the study) —by myeloid cells, breast tumor cells and mesenchymal stem cells." (PMID 33585241, 2020). "In parallel, inhibition of CXCL8 or of CXCR1/2 has increased the sensitivity of breast tumor cells to chemotherapeutic drugs, accompanied by reduced proportion of CSCs, angiogenesis, tumor growth and/or metastasis, with roles attributed to cyclooxygenase 2 (COX-2) in this process." (PMID 33585241, 2020). "Similarly to the findings obtained in non-transformed cells, RasG12V + p53shRNA had induced the expression of CXCL8 in breast tumor cells." (PMID 24598028, 2014). "This would mean that in breast tumor cells that express endogenously WT-Ras, CXCL8 may be induced by RTK ligands." (PMID 24598028, 2014).